MMP9 (matrix metallopeptidase 9)
Diseases named in the same sentence as MMP9 in open-access papers (continued):
Sharing a sentence is not in itself a finding about the gene and the disease.
bullous pemphigoid (8 papers, 2014 to 2026). Bullous pemphigoid (BP) is the most common form of autoimmune bullous dermatosis. "They demonstrated that the abundant component of BP blister fluid, MMP-9 (92 kD gelatinase), is produced by eosinophils and that MMP-9 degrades the collagenous domain of a recombinant form of the 180 kD bullous pemphigoid autoantigen in vitro." (PMID 37509055, 2023). "Mechanistically, MMP-9 has been shown to cleave the extracellular domain of the 180 kd bullous pemphigoid autoantigen in vitro, but not in vivo, thus questioning its direct role in causing the dermo-epidermal split." (PMID 34680139, 2021). "However, the stromal MMP-9 concentration did not vary between patients with KC and bullous keratopathy." (PMID 39177803, 2025). "Recently, MMP9 level was found to be induced by CXCL10 from monocytes and neutrophils but not lymphocytes in bullous pemphigoid patients, suggesting that the increased MMP9 in PBMCs stimulated with purified IgG from Jo1-positive sera, was perhaps due to monocytes." (PMID 31440381, 2019). "In patients with bullous pemphigoid, monocyte-derived macrophages, but not lymphocytes, respond to CXCL10 (upregulated by IL-17) by increasing MMP-9 release, potentially creating an inflammatory loop associated with disease outcome." (PMID 36911370, 2023).
chronic asthma (8 papers, 2009 to 2025). An asthma that is characterized by the development of persistent airway inflammation and recurrent attacks of breathlessness and wheezing, which vary in severity and frequency. "Our results showed increased thickness in the submucosa and basement membrane, as well as higher expression of MMP-9 in chronic asthma with rapid pulmonary function decline." (PMID 31547356, 2019). "Through increasing the thickness of the airway wall by collagen deposition, a decreased ratio of MMP-9/TIMP-1 in chronic asthma may result in airway obstruction." (PMID 31547356, 2019). "An increase in MMP-9 and MMP-9/TIMP-1 in airways or AMs could contribute to a greater decline in lung function in cases of chronic asthma and could therefore be used as an indicator of chronic airway inflammation." (PMID 31547356, 2019). "MMP-9 is known to be produced by several inflammatory or structural cells, including bronchial epithelial cells, eosinophils, mast cells, and alveolar macrophages, and these may have a greater contribution relative to neutrophils in chronic asthma." (PMID 31547356, 2019). "Most importantly, the MMP-9 level and MMP-9/TIMP-1 ratio produced from AMs were significantly decreased in chronic asthma with a slow FEV1 decline." (PMID 31547356, 2019). "Similarly, the chronic asthma-induced expressions of MMP-2, MMP-9, and COX-2 were strongly suppressed by BIBF1000 treatment." (PMID 36755351, 2023). "In a 5-year follow-up study, increased MMP-9 and MMP-9/TIMP-1 ratio in the fast FEV1 decline group in asthmatic bronchial biopsy specimens and alveolar macrophages imply their contribution to a greater decline in lung function of patients with chronic asthma." (PMID 33628848, 2021). "An increase in MMP-9 and MMP-9/TIMP-1 in airways or AMs could be indicators of chronic airway inflammation and contribute to a greater decline in lung function of patients with chronic asthma." (PMID 31547356, 2019). "This is in agreement with the results of prior studies on OVA-mediated chronic asthma models, and further indicates that rosuvastatin treatment leads to a significant decrease of not only Th2 cytokines, but also other mediators, including TNF-α, MMP9, and TGF-β1." (PMID 38913666, 2024). "Our results revealed that inhaled corticosteroids do not modify the expression of MMP-9 and TIMP-1 in AMs in patients with chronic asthma exhibiting a rapid decline in FEV1." (PMID 31547356, 2019).
cyst (8 papers, 2001 to 2023). A sac-like closed membranous structure that may be empty or contain fluid or amorphous material. "Here, we used the jck (juvenile cystic kidneys) mouse model which results from a double point mutation in the Nek8 gene to study the role of MMP9 in cyst progression." (PMID 38039285, 2023). "Zymography and immunofluorometric analysis of 61 cyst fluids showed a significant association between high trypsin concentrations and the activation of MMP-9 (P= 0.003–0.05)." (PMID 11355948, 2001). "In conclusion, we provide evidence that MMP9 is overexpressed in cystic tissue of the jck mouse model and exerts a protective effect on cyst formation, fibrosis and consequently increase the lifespan of the mice." (PMID 38039285, 2023). "In our model, the specific role of MMP9 on cyst formation is suggested by the steady levels of MMP2." (PMID 38039285, 2023). "With the growing body of literature on highly correlative biomarkers identified in cyst fluid analysis, the same research group sought to combine their nomogram with their proteomic biomarker models MMP9 and CA 72-4, sFASL, and IL-4." (PMID 32050465, 2020). "The 2 sets of markers (MMP9 and CA 72-4, sFASL and IL-4) were evaluated in the cyst fluid samples of 149 patients across 3 high volume institutions, with reported concordance indices of 0.76 and 0.8, respectively." (PMID 32050465, 2020). "In this study, we also compared other outcome indicators after treatment and showed that the combination was significantly better than the drugs alone, in terms of E2, P, CA-125, CA-199, MMP-2, MMP-9, Gal-3, VEGF, cyst size, and VAS." (PMID 36386543, 2022). "In addition, the combination showed significant advantages in other outcome indicators after treatment: E2, P, CA-125, CA-199, MMP-2, MMP-9, Gal-3, VEGF, cyst size, and VAS were significantly lower in patients on the combination than in those on the drugs alone." (PMID 36386543, 2022). "Consistent with previous studies showing that the proteolytic activity of MMPs might degrade collagen, fibronectin, laminin and contribute to cyst formation and expansion, the expression of MMP-2 and MMP-9 were upregulated in cystic VS samples compared with solid VS." (PMID 34646772, 2021). "As periostin is known to increase cell proliferation in ADPKD cyst epithelial cells, we estimated in vitro the physiological relevance of the periostin cleavage by MMP9 by quantifying the proliferation of IMCD-3 cell line, which do not produce MMP9." (PMID 38039285, 2023).
dental caries (8 papers, 2018 to 2025). The decay of a tooth, in which it becomes softened, discolored, and/or porous. "The GG genotype of MMP9 SNP (rs17576) has previously been associated with a lower risk of dental caries in the primary dentition." (PMID 32398053, 2020). "The aim of the study was to analyse Czech children with primary/permanent dentition polymorphisms in those genes encoding MMP2, MMP3, MMP9, MMP13, MMP16, and MMP20, which had been previously associated with dental caries in other populations." (PMID 32398053, 2020). "They found that human MMP-2, MMP-8, and MMP-9 were identified in demineralized dentinal lesions and inhibition of MMPs can reduce dentin caries progression." (PMID 29849633, 2018). "The same conclusion about the negative association with dental caries was reached in cases of MMP9 variants, in agreement with our results." (PMID 32398053, 2020). "In addition, there is a positive correlation between the quantity of MMP-9 in the dentinal fluid and the depth of the caries lesion, which clearly indicates that MMP-9 is a specific diagnostic indicator of dental caries." (PMID 31824679, 2019). "Several MMPs are reported in saliva apparently derived from salivary glands and gingival crevicular fluid out of which MMP-8 and MMP-9 are hypothesized as the abundant and predominant proteases in dentin caries especially in the outer layers of caries compared with the deep caries layer." (PMID 32071691, 2020). "There are seven key proteins involved in the action of curcumin on dental caries: MAPK1, BCL2, KRAS, CXCL8, TGFB1, MMP9, and IL1B, all of which spontaneously bind curcumin." (PMID 38920854, 2024). "The results showed that untreated dental caries were strongly correlated with elevated MMP-8 and MMP-9 salivary levels, and a positive relationship was observed for lesions affecting deciduous teeth." (PMID 35327715, 2022).
dissection (8 papers, 2014 to 2025). The separation and isolation of tissues for surgical purposes, or for the analysis or study of their structures. "Mechanistically, HAAPIR ameliorated aortic dissection by decreasing MMP9 (matrix metalloproteinase 9) levels and increasing α-SMA (α-smooth muscle actin) levels, with Mef2D as a direct downstream target." (PMID 40224357, 2025). "Therefore MMP-3 and MMP-9 can be considered as common mediators in the pathogenesis of both aortic dissection and atrophic striae." (PMID 24720641, 2014).
Duchenne muscular dystrophy (8 papers, 2016 to 2025). Duchenne muscular dystrophy (DMD) is a neuromuscular disease characterized by rapidly progressive muscle weakness and wasting due to degeneration of skeletal, smooth and cardiac muscle. "MMP-9 is increased in the hearts of dystrophin-deficient mdx mice, which possess point mutation in the Duchenne muscular dystrophy-related gene, and genetic ablation of MMP9 diminishes the activation of ERK1/2 and Akt kinase followed by an improvement in cardiac function." (PMID 34356671, 2021). "In this regard, it would be interesting to further investigate MMP9 and other metallopeptidases as biomarkers of disease progression, similar to what occurs in Duchenne muscular dystrophy." (PMID 35646913, 2022). "The increased abundance of the matrix metalloproteinase MMP9 agrees with the findings from the previous screening of serum from the mdx mouse and patients with Duchenne muscular dystrophy for minimally invasive biomarker candidates." (PMID 32916630, 2020). "Moreover, the upregulation of MMP-9 expression has been described in the muscles of mdx mice, an animal model of Duchenne muscular dystrophy." (PMID 28042204, 2016). "β‐DG could be cleaved by MMPs, especially MMP9, in Duchenne muscular dystrophy." (PMID 32790044, 2020). "In the mdx mouse model of Duchenne muscular dystrophy (DMD), MMP9 inhibition has been shown to reduce fibrosis, promote myofiber regeneration, and improve muscle structure and function." (PMID 40966415, 2025). "Muscle inflammation and oxidative stress are hallmarks of Duchenne muscular dystrophy, and the immuno-expression analysis of MMP-2 and MMP-9 revealed that these proteins are involved in muscle fibrosis in mdx animals." (PMID 36289739, 2022). "It has been known that matrix metalloproteinases, such as MMP-2 and MMP-9, play a critical role in the homeostasis and maintenance of myofiber functional integrity and that inhibition of MMP-9 improves myofiber regeneration in rodent models of Duchenne muscular dystrophy." (PMID 41009467, 2025).
epileptic seizures (8 papers, 2013 to 2025). "It is known that epileptic seizures and the associated changes in neuronal plasticity are MMP-9-dependent and require augmentation of expression as well as activity of the enzyme." (PMID 24918931, 2014). "Epileptic seizures are thought to induce inflammation and blood-brain barrier leakage which may be the cause of the increase in MMP-9 and S100B, along with other biomarkers in the serum." (PMID 40076533, 2025). "However the research conducted so far suggests a possibility of evaluation of MMP-9 as a potential marker of blood-brain barrier damage which increased concentration is associated with occurrence of epileptic seizures." (PMID 28104930, 2016). "Meanwhile, the serum MMP-9 level in patients with epileptic seizures was significantly higher than that in the control group." (PMID 38449733, 2024). "MMP-9 protein induction and the upregulation of its enzymatic activity at hippocampal synapses during epileptic seizures have been reported to be closely related to epileptogenicity." (PMID 39273208, 2024). "It has been reported that MMP-9 protein induction and the upregulation of its enzymatic activity at hippocampal synapses during epileptic seizures are closely related to epileptogenicity." (PMID 39273208, 2024). "The meta-analysis after pooling the data (df = 4, p < 0.00001; I2 = 99%) indicated that the serum MMP-9 level in patients with epileptic seizures was significantly higher than that in the control group (SMD = 5.19, 95% CI = 1.45–8.92, p = 0.006)." (PMID 38449733, 2024). "In another pentylenetetrazole model in mice, an increased expression and enzymatic activity of MMP-9 within the hippocampus were reported what was accompanied by epileptic seizures." (PMID 28104930, 2016). "In the research conducted so far an increased level of MMP-9 was reported in the blood serum of children who developed epileptic seizures." (PMID 28104930, 2016). "We measured significantly higher MMP-9 concentrations (P < 0.001) and QAlb values in seizure patients compared with controls." (PMID 23829879, 2013). "Our study aimed to determine whether MMP-9 can be measured in CSF of patients after epileptic seizures and whether there is a correlation between CSF MMP-9 levels and QAlb values in patients after epileptic seizures." (PMID 23829879, 2013). "Approximately 10% of MMP-9 WT mice developed PTE after CCI, and this percentage markedly increased in MMP-9 OE animals (50%) and decreased in MMP-9 KO animals, in which only 6% (1/15) developed seizures." (PMID 29667129, 2018). "However, the relationship between CSF MMP-9 and BBB dysfunction in patients after epileptic seizures remains unclear." (PMID 23829879, 2013).
glomerular diseases (8 papers, 2014 to 2025). "MMP9 has previously been shown to be produced by podocytes, and it is altered in several glomerular diseases, supporting the conclusion that Vangl2 modulates glomerular injury by stopping MMP9 production." (PMID 31500276, 2019). "Taken together, these studies support a key role of MMP-9 in podocyte injury and glomerular disease such as DN." (PMID 24454919, 2014). "Our results support that inhibition of PEC activation and MMP-9 production may represent a major opportunity for the prevention and treatment of proteinuric glomerular diseases." (PMID 25849723, 2015). "All these studies support a critical role of MMP9 in podocyte pathology and glomerular disease." (PMID 24454919, 2014). "Because MMP-9 degrades type IV collagen in GBM, it could be anticipated that MMP-9 may play a pivotal role in renal development and glomerular disease." (PMID 24454919, 2014). "However, the studies of MMP9 in glomerular disease are quite limited." (PMID 24454919, 2014). "Increased urinary excretion of matrix metalloproteinase-9 (MMP-9) and nephrin has been reported in a number of IMN-like glomerular diseases in which they reflected disease severity." (PMID 34707724, 2021). "Although the potential of MMP-9 to reflect the severity of IMN has not been studied, MMP-9 is a recognized player in the pathogenesis of several glomerular diseases." (PMID 34707724, 2021).
gout (8 papers, 2022 to 2024). A condition characterized by painful swelling of the joints, which is caused by deposition of urate crystals. "MMP-9 may serve as a biomarker and risk predictor for gout and DED, and modulation and inhibition of MMP-9 may be an important therapeutic strategy for gout and DED." (PMID 38376774, 2024). "Gout patients stimulate the production of MMP-9 directly or indirectly by macrophages due to urate crystals in the body, which in turn causes inflammation and tissue damage." (PMID 38376774, 2024). "Some studies support that quercetin significantly reduces the relative expression of MMP-9 in gout patients and has the potential to be developed as a dietary supplement for the prevention and management of gouty arthritis." (PMID 38376774, 2024). "Studies have shown that the activation of MMP2 and MMP9 in GA SF samples can reveal the inflammation of the knee joint in gouty arthritis." (PMID 38066599, 2023). "In this study, we proposed the molecular mechanism of ozone in the treatment of gout pain through AMPK/Gas6/MerTK/SOCS3/MMP9 for the first time." (PMID 38066599, 2023). "Hyperuricemia also promotes inflammation and the expression of MMP-9 in individuals with gouty arthritis." (PMID 36710339, 2023). "Hyperuricemia also promotes inflammation and the expression of MMP-9 in the synovial fluid of patients with gouty arthritis." (PMID 36710339, 2023). "Increased expression of MMP-9 in gout patients may be involved in the degradation of ECM components in gouty arthritis, and its increased activity may lead to gout attacks." (PMID 38376774, 2024). "MMP-9 is induced by key cytokines in the early stages of the inflammatory cascade response and is an ideal biomarker, and its expression levels are closely related to the progression of gout and DED." (PMID 38376774, 2024). "Chemokines such as MMP-9 and CCL-2 contribute to the inflammation associated with gouty arthritis." (PMID 36297105, 2022). "Also, the expression of the downstream targets ITGAV and MMP9 were increased in gout patients." (PMID 36850003, 2023). "As a first exploration, mRNA levels of TGFB1, TGFBRI, TGFBRII and three TGF-β target genes ITGAV, MMP9 and SMAD7 were compared between untreated adherent monocytes of patients with gout and age and sex matched healthy controls." (PMID 36850003, 2023). "In addition, we found strong and high confidence (> 0.700) interactions between known gout mediators and EFS identified proteins, particularly in the proteins identified at 48wks of ULT, including MMP9." (PMID 39426967, 2024).